CD4 (CD4 molecule)
Diseases named in the same sentence as CD4 in open-access papers (continued):
Sharing a sentence is not in itself a finding about the gene and the disease.
infection (continued). "Since both CD4 + and CD8 + T cells induce IFNγ+ during C. auris primary infection, we examined the contribution of CD8 + T cells in regulating C. auris during reinfection." (PMID 40294061, 2025). "During primary infection, DENV enters via the skin and is presented by antigen-presenting cells (APCs) through MHC II to CD4+ T cells, which help activate naïve B cells in lymphoid tissue." (PMID 41305369, 2025). "We found significant correlations between the proportion of CD3+, CD4+, CD8+, and B220+ cells with control of infection, with larger proportions of these cells corresponding to lower CFU in the lung." (PMID 40937719, 2025). "The results showed that the expression of CD3, CD4, and CD8 was intense in the blood vessels of the control group, while in the infection group, the CD3, CD4, and CD8 protein immunostaining was decreased (p < 0.001)." (PMID 40305201, 2025). "Among the signals from LZ GC B cells to DCs, multiple MHC II protein complex subunits exhibited enhanced interaction with Cd4, while signals including Fcer2a-(Itgax+Itgb2) and Cd22-Ptprc were weakened by PCV2 infection." (PMID 41011514, 2025). "All patients with stage I infection had a robust Ab response (>500 BAU/mL) and a positive CD4+ response." (PMID 41210962, 2025). "In line with this, reduced pro-inflammatory CD4 and CD8 T cell responses and corresponding cytokines IFN-γ and GzmB were found in TRαGS mice upon infection." (PMID 41159501, 2025). "Nine days post‐infection, there was an increase in the expression of cell‐surface CD154 in CD4+ T cells together with increased IL‐13 levels in the cavity, suggestive of local antigen presentation." (PMID 41388224, 2025). "Evidence suggests that vaccination strategies generate HPV-specific CD4+ and CD8+ T cells and that at least some of them home to the infection site." (PMID 40430784, 2025). "XBB.1.5-infected mice were intraperitoneally injected with depleting antibodies (anti-CD4 or anti-CD8; 200 μg/mouse) on days -3 and -1 prior to infection, and subsequently on days 1, 3, 6, and 12 post-infection." (PMID 40822581, 2025). "In the current study, we observed a significant increase in CD4+ and CD8+ T cell populations in the lungs of C57BL/6 mice following XBB.1.5 infection, indicative of a robust adaptive immune response." (PMID 40822581, 2025). "Immunocompetent patients mounted a robust CD4+ and CD8+ T cell response, characterized by a predominant TCM profile as previously been reported post-infection." (PMID 40431250, 2025). "CD4+ T cells served as a reservoir for HIV, with increased antigenic and inflammatory loads during infection leading to greater immune activation and exhaustion in PLWH compared to healthy controls." (PMID 40838719, 2025). "The role of Gpx4 is vital for the survival of CD8+ T cells, as well as the proliferation of CD4+ and CD8+ T cells during infection." (PMID 40070882, 2025). "We also performed flow cytometric staining of CD4+ and CD8 + T cells in the gut of wild type and PINK1 KO mice following infection." (PMID 40404738, 2025). "At 10 weeks post-infection, mice immunized with ESAT6 + GLA-SE/CDG exhibited an increased frequency of Ag-specific CD4+ Trm-like cells in the lung parenchyma compared to those with ESAT6 + GLA-SE immunization." (PMID 40414893, 2025). "To further explore the immunomodulatory effects of baicalin, we examined the changes in splenic T lymphocyte subpopulations (CD4+ and CD+) and calculated the CD4+/CD8+ T-cell ratio by flow cytometry at days 3 and 6 post-infection." (PMID 40406095, 2025). "Subsequently, flow cytometry was used to assess both the composition and activation of CD4+ and CD8+ T cells in the brain during TMEV infection." (PMID 40270964, 2025). "Treatment with antiretroviral therapy (ART) is capable of inhibiting HIV replication, promoting CD4+T-cell activation and hence effectively controlling HIV infection, which allows patients to be vaccinated prior to late-stage infection." (PMID 40006926, 2025).
infection (continued). "In vitro experiments also demonstrated a preferential infection of HSPCs double-positive for CD4 and CXCR4 over CD4 and CCR5." (PMID 40980600, 2025). "Carriers exhibited significantly lower proportions of IFN‐γ‐expressing CD4+ and CD8+ T cells during early infection, accompanied by reduced peripheral B‐cell frequencies and elevated OPF sIgA levels during persistent infection." (PMID 41473407, 2025). "To investigate the contribution of T-cells to the mortality of older mice, we depleted T-cells by administering anti(α)-CD4 and α-CD8 treatments to young WT and middle-aged WT mice and aged WT mice before and after infection." (PMID 40720380, 2025). "We conclude that microglia, CD4+ T cells, and macrophages contribute to the overall production of IFN-γ following an intranasal infection with JHMV." (PMID 39803452, 2025). "The frequencies of total CD4+ and CD8+ cells over time were affected similarly by infection in both groups." (PMID 40027795, 2025). "Infection by the HIV leads to persistently decreased levels of CD4 T cells, increased levels of CD8 T cells, and the inversion of CD4/CD8 ratio." (PMID 41216008, 2025). "The bovine immune response is Th1-dominant, with CD4+ and CD8+ T-cells promoting IFN-γ production for bacterial control, while γδ T-cells play a role in early containment of infection." (PMID 41169614, 2025). "They phagocytose pathogens or particles in submucosal tissues and transport them to draining lymph nodes, where they present the antigens to CD4+ T cells and activate CD8+ cytotoxic T cells, initiating immune control of the infection." (PMID 40130873, 2025). "CD4+ and CD8+ specific T cells can be detected seven days after infection and remain detectable for years." (PMID 40170841, 2025). "Upon infection, CD8+ and CD4+ T cells in old mice showed marked reduction in clonal expansion and upregulation of immune checkpoints associated with T cell exhaustion." (PMID 40396260, 2025). "An effective immunotherapy will generate HPV-specific CD4+ and CD8+ effector T cells at the site of infection and will overcome local suppression or inhibition of effector T cell function." (PMID 40430784, 2025). "CD4+ T‐cell and CD8+ T‐cell immune responses are mounted after smallpox vaccination and MPXV infection." (PMID 41281187, 2025). "The progressive destruction of CD4+ T cells, exhaustion of CD8+ T cells, and alterations in regulatory and memory T cells contribute to the complexity of infection control and viral persistence." (PMID 41157651, 2025). "Hepatocyte-specific CD155 knockout reversed T-cell exhaustion, restored CD4+ and CD8+ T-cell functionality, and significantly reduced lesion size and number in the infection mouse model." (PMID 40666808, 2025). "CD27, a T‐cell costimulatory molecule, supports antigen‐specific expansion of naïve T cells, is essential for the primary CD4+ and CD8+ T‐cell responses to infection, and plays a crucial role in the generation of T‐cell memory." (PMID 40746087, 2025). "Patients that remained free from late infections had higher Δscore for T CD3+ (0.524 vs 0.263, p=0.018) and T CD4+ (0.452 vs 0.287, p=0.036) than those who developed late infections." (PMID 40574851, 2025). "In the transition process of the virus, HIV-1 envelope glycoprotein interacts with the primary receptor CD4 and coreceptor CCR5 or CXCR4 to enter the host cells and produce the infection." (PMID 41181130, 2025). "Flow cytometry analysis displayed significantly higher percentages of CD4+ Th and lower percentages of CD8+ Tc cells in individuals recovered from mild symptomatic infection compared to those recovered from asymptomatic infection (p < 0.05 in each)." (PMID 39963186, 2025). "Key parameters of infection (IL-6, TNFa, D-dimer, CRP and CD4+ T cell counts) were correlated (Spearman) with lipid concentrations at critical time points of infection and treatment." (PMID 40129985, 2025).
infection (continued). "Nef function was assessed as the downregulation of cell surface CD4 and MHC-I after infection of SUPT1 cells for 48 hours with participant-specific Nef PSVs." (PMID 40552830, 2025). "CD38, the most reliable surrogate marker for T cell immune activation, was significantly upregulated at the early stage of infection (day 1) in a subset of both CD19+ B cells and CD4+ T lymphocytes." (PMID 40733503, 2025). "This impaired cellular immunity was restored after natural infection, as demonstrated by enhanced antigen-specific CD4+ and CD8+ T-cell activation post-infection." (PMID 40977733, 2025). "In the present investigation we reported that SRB-treated mice exhibited a considerable elevation of CD4+ T cells and an increase in CD8+ T cells in the chronic model of infection and therapy." (PMID 40771802, 2025). "Despite complete viral clearance and full recovery of body weight by day 8 post‐infection, both CD4+ and CD8+ T cells remained detectable in the lungs up to day 28 post infection, indicating ongoing immune activity." (PMID 40851359, 2025). "Nonetheless, they demonstrated that DC3s had a high protein expression of the HIV entry receptors CD4, CCR5 and CXCR4, indicating the capacity for second-phase transfer and productive infection." (PMID 39861894, 2025). "A recent study reported that spike-specific CD4+ and CD8+ T cells from individuals with previous infection or vaccination displayed strong immune recognition of the highly mutated BA.2.86 variant." (PMID 40170841, 2025). "Both infection and vaccination from SARS-CoV-2 can induce robust CD4+ T cell responses promoted by an IL-6 amplifier loop of inflammation." (PMID 40552181, 2025). "Carriers exhibited significantly lower frequencies of IFN‐γ‐producing CD4+ and CD8+ T subsets during early infection and diminished peripheral B‐cell frequencies alongside elevated OPF sIgA levels during persistent infection." (PMID 41473407, 2025). "The results of flow cytometry showed that PECP significantly inhibited the reduction of CD3+ and CD4+ cell ratios, the reduction of CD4+/CD8+, and the elevation of CD8+ cell ratios in mice after infection." (PMID 40757669, 2025). "The top 7 variables ranked by VIMP were included in the final RSF model: hemoglobin, age, infection route, WBC, education level, CD4, and BG." (PMID 40456121, 2025). "Diverging from s.c. infection dynamics, systemic LCMV infection notably induces a dual polarization of CD4+ T cells into both TH1 and TFH subsets." (PMID 40169810, 2025). "Eight days after infection, GFP-Irf4+/fl, GFP+Irf4+/fl, GFP-Irf4-/fl and GFP+Irf4-/fl CD4+ T cells were sorted and analyzed by single cell ATACseq (assay for transposase-accessible chromatin sequencing)." (PMID 40726986, 2025). "This adds to our claim on the importance of CD4+ T cell vaccine-induced priming, as the occurrence of such cross-binding clones at higher quantities may prove to be of lower efficacy to control subsequent infections in the real world and potentially promote detrimental effects with severe cases." (PMID 41295476, 2025). "Upon infection, these mice demonstrated a lower Th1 cytokine response (TNF-α and IFN-γ) and reduced CD4+ and CD8+ T cell production." (PMID 40435099, 2025). "Since venetoclax reduces both the levels of CD4+ T-cells and their frequency of infection, the reduction in the size of the SIV reservoir was even more evident when considering the absolute quantification of the number of CD4+ T-cells harboring intact SIV DNA." (PMID 40709247, 2025). "After monocyte-derived macrophage (MDM) differentiation and infection with Mtb strain H37Rv at an MOI of 4–5, we cocultured infected MDMs with autologous memory CD4+ T cells." (PMID 40990918, 2025). "The protective advantage of hybrid immunity likely arises from a combination of higher numbers of SARS-CoV-2-specific MBCs, elevated neutralizing antibody titers, and an infection-induced cytokine profile of IFN-γ and IL-10 in CD4+ T cells." (PMID 40170841, 2025).
infection (continued). "During the germinal center reaction, a subset of cognate CD4+ T cells, the T follicular helper (TFH) cells, help activate and differentiate B cells and help in antibody production during infection." (PMID 40431664, 2025). "When analyzing the memory cell subsets within the AIM+ DENV-specific T cells, we found a higher frequency of Temra cells in CD4+ T cells and CD8+ T cells among children with subsequent inapparent infections." (PMID 39989460, 2025). "We show that,when recalled by infection during pregnancy, IAV-specific memory CD4+ T cells retain protective antiviral TH1 characteristics." (PMID 39744951, 2025). "The results of our study confirm that infection with P. berghei ANKA results in the expansion and activation of splenic CD4 and CD8 T cells." (PMID 40720541, 2025). "To assess the impact of CD4+ T cell depletion on Ab responses to primary DENV2 infection, we measured virus-specific IgM and IgG levels after infection." (PMID 41295476, 2025). "An early immune response involving the development of Th1-type CD4+ and CD8+ T cells can resolve infection and produce long-lasting immunity." (PMID 41471158, 2025). "As expected, the frequencies of CD4 + T cells significantly declined after 6 weeks of HIV infection, was reversed by ART, but then declined again during rebound infection (right)." (PMID 39952916, 2025). "Ephrins have an important role in inflammatory and immune response to infection, including CD8 and CD4 T cell migration, and further have been shown to regulate endothelial and lung vascular permeability during injury." (PMID 40170544, 2025). "The CD4 CM and EM TIGIT cell types were also predictive of freedom from infection in a time-based analysis, especially with incorporation of induction immunosuppression with ATG." (PMID 40475763, 2025). "Our model provided an opportunity to examine specific infection sites and revealed LANA-specific CD4+ T cells within the early differentiated effector compartment in the peritoneum." (PMID 41350288, 2025). "The most significant difference was for CD4 CM expressing CD25, for which frequencies were only elevated before infection compared to uninfected controls." (PMID 40475763, 2025). "Human immunodeficiency virus (HIV) belongs to the retrovirus family, and infection with HIV attenuates the immune system extensively, including in terms of CD4+T-cell depletion and diminished immunity." (PMID 40006926, 2025). "This shift in CD4+ T and CD8+ T cells after PAB treatment is beneficial for infection control because it promotes the activation of immune cells directly involved in parasite destruction." (PMID 39944494, 2025). "Adult CD4+ T cells showed inhibited Tbet induction in the neonatal CD45.1 host, phenocopying neonatal cells in primary infection." (PMID 40280180, 2025). "Here, we expanded our analysis of T cell subsets and observed a significant expansion of CD4+ and CD8+ effector, Trm, and central memory (Tcm) subsets during the late phase of infection." (PMID 39807873, 2025). "One week after HIV infection, 36% of infected hDRAGA showed a decline in CD4:CD8 ratios from baseline, and this percentage increased to 87.5% by 4 weeks post-infection." (PMID 41332665, 2025). "Their work also highlights the critical role of CD4 deregulation in HIV infection, showing that higher CD4 levels are necessary for viral entry and efficient productive infection in an in vitro model." (PMID 39774439, 2025). "Based on our findings, we propose that measuring serum Ig levels, T (including CD4+ and CD8+ subsets), B and NK lymphocytes at PreTx, 1M, 6M and 12M provides a comprehensive assessment of immune recovery and identifies late infections risks." (PMID 40574851, 2025). "In particular, it has been reported that CD4+ and CD8+ T cell responses have a significant influence on infection outcomes." (PMID 40739075, 2025).
infection (continued). "Interestingly, even during adequate HAART therapy, viral Nef has been found to accumulate in HIV and SIV infected cardiomyocytes, which may explain why HIVAC is prevalent even when the infection is considered clinically well-controlled with normal CD4 counts and low viral load." (PMID 39086659, 2024). "In parallel, they backed this up by analyzing synchronously infected primary CD4+ T cells, resulting in a detailed overview of HIV-elicited proteomic changes at 24 and 48 h post-infection." (PMID 38543785, 2024). "Pre-existing CD4+ and CD8+ T cells to HAdV-C5 were detected in all donors and were also able to cross-react with ChAd6 and ChAd7, with which previous infection is extremely unlikely." (PMID 38932265, 2024). "The CD80 signaling pathway related to T-cell activation was increased at 6 w after infection, and increased expression of its receptor CD28 on the surfaces of CD4+ and CD8+ T-cells was confirmed by flow cytometry, suggesting an increase in their activation." (PMID 39590301, 2024). "In summary, our data indicates that CD4+ and CD8+ T cell responses are relatively stable for at least 6 months, which can provide sufficient protection against future infections and severe illness occurrence." (PMID 38793715, 2024). "Here, we report that BTLA levels are significantly increased in the circulating and intrahepatic CD4+ T cells from patients with HBV-ACLF, and are positively correlated with disease severity, prognosis, and infection complications." (PMID 38418488, 2024). "Meanwhile, two doses of one-quarter the standard dose (25 μg/dose) of the mRNA-1273 vaccine induced robust CD4+ helper T cells, CD8+ cytotoxic T cells, and humoral immune responses, which was comparable to natural infection." (PMID 38550714, 2024). "Studies of the immune response to other thermally-dimorphic fungi show that innate immune cells, such as macrophages and dendritic cells, cooperate with the adaptive immune cells, such as CD4+ and CD8+ T cells, to control infection." (PMID 38198478, 2024). "During the acute phase of infection, MDV induces lytic infection in B and T lymphocytes and subsequently establishes latent infection in mainly infected CD4+ T cells." (PMID 38275925, 2024). "Results were consistent in sensitivity analysis where additional covariates, including age, CD4+ T-cell count, CD4+/CD8+ T-cell ratio and recent infection were included." (PMID 38698440, 2024). "Model outputs suggest that the innate immune response plays a crucial role in controlling early infection, while SARS-CoV-2 specific CD4+ T cells correspond to later viral elimination, and anti-spike IgG antibodies do not impact viral dynamics." (PMID 39575237, 2024). "Previous studies have shown that following a primary Eimeria infection, CD4+ and CD8+ T lymphocytes increase shortly after primary infection, but decrease during later infection in the small intestine." (PMID 38492183, 2024). "Next, we measured the proportions of CD3+, CD4+, and CD8+ cells in the blood to assess the cellular immune responses after infection." (PMID 38674684, 2024). "Further, during infection (9 days post-infection), lpr and gld mice showed significantly increased counts of NK and CD8+ T-cells as well as of CD4+ T-cells compared to wild-type mice (p ≤ 0.05)." (PMID 39339840, 2024). "In both MtbΔpdtaS and MtbWT-vaccinated mice, a similar proportion of activated lung CD4+ T cells and CD8+ T cells was observed at day 10 post-infection; however, these responses contracted over time." (PMID 38250863, 2024). "We examined IFNγ-, IL17A-, and IL17F-producing T cell subsets, including γδ+, CD4+, and CD8+ T cells, after 14-days post-infection." (PMID 39475280, 2024). "We infected HeLa, THP1, as well as HIV-negative study participants-derived CD4+ T cells and found that, compared with uninfected control cells, HIV-1 NL4-3 infection induced significant cytoplasm-to-nucleus translocation of RPLP1 by confocal microscopy." (PMID 38906865, 2024).